CD4 (CD4 molecule)
Diseases named in the same sentence as CD4 in open-access papers (continued):
Sharing a sentence is not in itself a finding about the gene and the disease.
tumor (continued). "It is certain that elevated lactate levels not only inhibit the anti-inflammatory and anti-tumor effects of immune cells such as CD4+ T cells, CD8+ T cells, NK cells, and NKT cells but also benefit immunosuppressive cells such as Treg cells." (PMID 37724112, 2023). "The adaptive immune system, composed of CD8+ T and also CD4+ T cells, and B cells, plays a pivotal role in mounting an effective, antigen-specific immune response against tumours." (PMID 37516825, 2023). "With disease progression from LPT to LNPT to LKT genotypes we saw a decrease in CD3+ve T lymphocytes and significant decreases in the number of CD4+ve T cells present both within and at the margins of tumours (Supplementary Date File 15)." (PMID 37626054, 2023). "The mean frequency of resting anti-tumor memory CD4 T-cells in unchallenged spleen was 0.028% and of memory CD8 T-cells was 0.11% which was not high enough to distinguish them from background." (PMID 37033929, 2023). "This is further supported by combinatorial PD-1 mAb coupled LSD1-inhibition therapy in exhibiting superior reduced tumor progression/tumor metastasis, reduced CD4+/CD8+ T cell ratio, and increased nodal CD3+/CD8+ T cell populations." (PMID 36826125, 2023). "Compared to normal tissues, immune cells, including plasma cells (P < 0.001), activated memory CD4+ T cells (P < 0.001), regulatory T (Treg) cells (P < 0.001) and macrophages M1 (P < 0.001), were more abundant in tumor tissues." (PMID 37280525, 2023). "HPV-related cancers proliferate due to poor CD4+-mediated cytokine secretion, CD8+-associated cytotoxicity, and tumor penetrability, along with a high influx of regulatory CD4+ FOXP3+ T cells." (PMID 37513985, 2023). "CD8+ effector cells have poor infiltration rates in tumors, whereas CD4+ T effector cells show high infiltration rates while simultaneously stimulating tumor antigen-specific CD8+ T cells." (PMID 38328405, 2023). "AIM2 accelerated tumor development by reducing CD4+ effector T cells while increasing the number of Treg cells." (PMID 37752941, 2023). "We next used scRNA-seq and CyTOF analysis to assess CD4+ T-cell heterogeneity within the tumor microenvironment." (PMID 36689623, 2023). "The PD1 receptor can be expressed on CD8+ and CD4+ T-cells, whereas PD-L1 is expressed in activated T-cells, tumor-infiltrating macrophages or fibroblasts, and tumor cells." (PMID 36931099, 2023). "PD1 expression on T-cells increased with disease stage with pT3-4 RCC tumours, locally advanced tumours and metastatic sites displaying the highest expression of PD-1 on CD4+ and CD8+T-cells." (PMID 37940720, 2023). "The immune cell groups CD4 T-Cells, macrophages, and monocytes had the highest fractions in many of the tumor samples." (PMID 37400526, 2023). "TNBC patients with high stromal STAT3 had reduced CD4+ T‐cell infiltrates within the tumour (p = 0.001) and higher tumour budding (p = 0.003)." (PMID 37199043, 2023). "While many studies have focussed on CD8+ T cells, the importance of CD4+ T cells for tumour control and response to immunotherapy approaches is becoming apparent." (PMID 37190281, 2023). "Treatment with OAd-MSC TLR4−/− also induced increased density of tumor-infiltrating T cells, as well as a lower CD4+/CD8+ ratio." (PMID 36875156, 2023). "High mtPCDI were broadly associated with higher levels of CD4 Naive, CD8 Effector, CD8 Naive, DC, Monocytes CD14, Monocytes CD16, NK, pDC, Plasma, and Th cells in the TCGA LGG developed for tumour characteristics." (PMID 37660060, 2023). "Of note, as a key regulator of anti-tumor immunity, miR-142-5p inhibited PD-L1 expression on tumor cells in vitro enhancing tumor infiltration by CD4+- and CD8+-lymphocytes." (PMID 35171328, 2023). "Different cell types, including tumor cells and human CD4+ Th17 cells, internalize mitocepted MSC mitochondria." (PMID 36694226, 2023).
tumor (continued). "Our results demonstrated that allogenic ML-NK cells were able to extravasate and penetrate patient derived tumor spheroids, although the presence of CD4 T cells sped up this process." (PMID 37865647, 2023). "C5aR signaling contributes to MDSCs function by regulating CD4+ T cells are polarized to Th2 type in the lungs of tumor-bearing mice." (PMID 37465670, 2023). "Further analysis of tumor-infiltrated immune cells showed a further dramatic increase in both CD4+ and CD8+ T cells." (PMID 38038129, 2023). "Accumulating evidence confirms that CD4+ T cells target tumor cells by directly eliminating them via cytolysis or by indirectly regulating the tumor microenvironment (TME)." (PMID 37711621, 2023). "Tumor cells have been demonstrated to play a direct role in the expansion of CD4+ T cells, thus further inhibiting antitumor immunity due to T cells." (PMID 36941336, 2023). "Very few adoptively transferred ovalbumin-specific dsRed+ OT-II CD4+ TCRtg T cells clustered locally within the tumour invasive margin and arrested both in the stromal and the tumoural compartment." (PMID 37316667, 2023). "Tregs, a subpopulation of CD4+ T cells, which are frequently linked to a poor prognosis for HCC, directly promote tumor escape through a variety of contact-dependent and contact-independent mechanisms and severely suppress immunological responses." (PMID 37426702, 2023). "Dimensionality reduction analysis revealed that CD4 T cells clustered primarily by the tissue of origin (blood vs. tumor) and tumor growth outcome (progression vs. regression)." (PMID 37185301, 2023). "TUDCA treatment to B16F10-bearing WT mice suppressed tumor growth and decreased PD-1 expression on CD4 T cells." (PMID 37147330, 2023). "mIHC was conducted, and the relationships between the tumor-infiltrating Tim-3+ cDC2 or CD4+ T cells and the therapeutic response were evaluated." (PMID 37771774, 2023). "Oral administration of LGG-JP significantly enhanced the effect of cancer vaccine in inhibiting tumor growth, as well as an enhanced the proportion of CD4+ T cells and CD8+ T cells infiltration in tumor microenvironment." (PMID 37435064, 2023). "Because CD4+ CTLs mediate cell death in an HLA class II-restricted manner, we examined the proximity of CD4+ CTLs and tumor cells expressing HLA-DR by multicolor IF staining." (PMID 38077321, 2023). "In contrast, specific depletion of CD163 macrophages results in tumor regression and massive infiltration of activated T cells, including both CD4+ and CD8+ cells." (PMID 37176042, 2023). "The abundance of cell−cell interactions in mast cells/CD4 T cells/S100A8+ macrophages/tumor cells compared to other cells was higher in responders than in nonresponders." (PMID 37152010, 2023). "As key antigen-presenting cells (APCs), the two conventional subsets, cDC1 and cDC2, are responsible for the presentation of tumor-associated antigens to CD8+ T cells and CD4+ T cells, respectively." (PMID 37675100, 2023). "Ths cells are generated by cytokine-specific polarization or TCR-signaling activation in the TME, and they can assist CD4+ T lymphocytes in producing cytotoxicity and destroying tumor cells." (PMID 37513975, 2023). "In a mouse model of breast cancer, induction of TGF-β receptor II gene deletion in CD4+ T cells inhibited tumor growth." (PMID 36776289, 2023). "Our initial data showed that CD4+ effector T cells and innate immune stimulation independently promoted the recruitment of immature monocytes into the tumour microenvironment." (PMID 37316667, 2023). "This increase in therapeutic activity was associated with increased CD4+ and CD8+ T cell and decreased Treg tumour infiltration, and an increase in the proportion of activated and effector memory and central memory T cells." (PMID 37627206, 2023). "The impaired tumor immunity in young adult M-Traf3-/- mice with MDSC hyperexpansion was associated with an altered phenotype of CD8 T cells, CD4 T cells, and NK cells." (PMID 37207205, 2023).
tumor (continued). "In tumor‐bearing mice one week post‐treatment, miRNA treatment led to increased accumulation of CD4+ and CD8+ T cells (p<0.001) and decreased intertumoral Tregs (p<0.05)." (PMID 37520581, 2023). "CD4+ memory T cells inhibit tumor cell growth by promoting the proliferation of CD8+ memory T cells." (PMID 37665670, 2023). "Proliferation of restimulated cells from tumor-bearing vehicle-treated mice was 31.3% ± 5.9 and 17.5% ± 3.1 for CD4 and CD8 T cells, respectively." (PMID 36913398, 2023). "As well, spleen, blood, and BM of tumor-bearing mice became dominated by Neut/MDSCs and had diminished B cells, CD4+, and CD8+ T cell populations." (PMID 36911097, 2023). "Our analysis of immune cell subtypes and immune checkpoint gene expression revealed that the PTMC-Inf tumor shares the same characteristics (more infiltrating CD4 + and CD8 + T cells, and high expression of PDL1, PDCD1, and CTLA4)." (PMID 36941725, 2023). "Its overexpression characterizes so-called exhausted T cells (especially CD8+, but also CD4+, and particularly, among the latter, CD4+ Treg Foxp3+, but also Th17) in the setting of tumours." (PMID 36980583, 2023). "Tumor-antigen-specific CD4 T cells are frequently detected in cancer patients, and vaccination that boosts tumor-antigen-specific CD4 and CD8 T cells has resulted in clinical benefit including cases of complete response." (PMID 37185301, 2023). "Recent studies have shown that the CD4+ T-cell also impacted the anti-tumor efficacy of other Listeria-based vaccines." (PMID 36831577, 2023). "The enhanced recruitment of CD4+ T cells is dependent on host type I interferon signaling, consistent with the well-known role of interferon in anti-tumor response." (PMID 38196632, 2023). "More researches mainly focused on the interaction of CD8+ T lymphocytes and tumor microenvironment, and ignored the important role of CD4+ Th cells in coordinating the innate and adaptive immunity." (PMID 38102684, 2023). "CD4+ TILs exhibited heterogeneous expression of both T-bet and FoxP3 in established tumours (D14 & D21), while CD4+ TILs in early-stage tumours (D7) were mainly FoxP3-T-bet- (75% of total CD4+ TILs)." (PMID 37153625, 2023). "Among lymphocytes, the number of CD8+ lymphocytes was higher compared to that of CD4+ lymphocytes, both in the tumor and peri-tumoral compartments and normal pancreatic parenchyma (49.6 vs. 37.8, p = 0.04, 26.3 vs. 11, p < 0.001, respectively)." (PMID 37366900, 2023). "Recent experimental data have suggested Tregs derived from CD4 + T cells or Treg subsets can be eliminated in the tumour environment by immunotherapy that is aimed at blocking Foxp3, together with the selective inhibition of other minor Treg subsets." (PMID 37670247, 2023). "KRAS inhibition in immunocompetent mouse tumor models reversed this phenotype and resulted in an increased M1/M2 macrophage polarization ratio as well as increased tumor-infiltrating CD4+ and CD8+ T cells." (PMID 37444422, 2023). "T-cell co-stimulation is a hierarchical process that is crucial for the formation of an effective immune response, while Tregs are a subpopulation of CD4+ T cells that play a critical role in tumor immune escape and angiogenesis." (PMID 37275958, 2023). "In the vicinity of the tumor, Tregs can increase in proportion to as high as 20-30% of CD4+ T cells." (PMID 37637032, 2023). "The number of high-frequency unique anti-tumor memory TRB clonotypes in the donor spleen varied from 1 to 8 for CD4 and 5-7 for CD8 T-cells with a median of 3 CD4 T-cells and 6 CD8 T-cells." (PMID 37033929, 2023). "Slightly higher percentages of CD4+ T cells and myeloid cells are observed at least in the initial phase of tumor growth." (PMID 37503343, 2023). "CD4 + Th1 cells assist cytotoxic T lymphocytes and impress tumor progression by the production of cytokines (for example, IFN-γ), Th17 cells, and Treg cells function in the anti-tumor process by activating cytotoxic lymphocytes or suppression of inflammation." (PMID 37880772, 2023).
tumor (continued). "These clusters comprised tumor cells expressing different levels of HLA-DR (Clusters 2 and 4), CD4+ and CD8+ T cells (Clusters 3 and 8), mononuclear phagocytes (MNPs) (Clusters 5, 6, and 7), and one cluster with low expression for all markers (Cluster 1)." (PMID 37731497, 2023). "Currently, it is known that CD4+ T cells have a variety of ways to kill tumor cells, and memory T cells are a subset of CD4+ T cells." (PMID 37274740, 2023). "DMBA3-4 tumor growth was further accelerated in WT mice that underwent CD8+ T plus CD4+ T cell depletion." (PMID 37843274, 2023). "Adoptively transferred tumor-antigen-specific mouse CD4 T cells are sufficient to elicit potent tumor control in lymphopenic or Rag KO mice." (PMID 37185301, 2023). "Specifically, this correlation was observed in patients with BRCA and its subtypes (basal, HER2, and luminal), where reduced KLRB1 expression levels were linked to tumor purity, B cells, CD8+ T cells, CD4+ T cells, neutrophils, and dendritic cells." (PMID 37988189, 2023). "Naïve CD4 + T cells can differentiate into each type of the mentioned cells following exposure to antigens and the released cytokines within the tumor milieu." (PMID 37221555, 2023). "CD4 T cells from both healthy persons and MCC patients recognize LT, making it an attractive tumor-associated antigen for vaccine development." (PMID 37711623, 2023). "The aggregate of plasmid DNA encoding ovalbumin (OVA) (referred to as pOVA) vaccine with pVAX-α-PD-1 caused enormous tumor regression, which is often attributed to the elevated cytokine stage and proportion of CD8+ T and CD4+ T cells in tumors." (PMID 37138873, 2023). "We also found that the relative frequency of regulatory T cells (FoxP3+CD4+ T cells) was higher in FN-positive tumor tissues than in those FN-negative tumors in the analysis of CD4+ T cells (P=0.0014)." (PMID 36960042, 2023). "When treated with MIH and RT (6-MV X-rays), there was a substantial decrease in tumor volume and lung metastasis, improvement in survival and Bax expression, and greater CD4 + T cell percentage and CD4 + /CD8+ cell ratio than with RT or MIH alone." (PMID 37107299, 2023). "Based on their phenotype, TILs can be classified as CD8+ T cells, CD8+ tissue-resident memory T cells, CD4+ T helper cells, CD4+ regulatory T cells, CD4+ follicular helper T cells, and tumor-infiltrating B cells." (PMID 37760449, 2023). "We found that TRIM28 expression enhanced immune cell infiltration, especially in BRCA, GBM, LIHC, and PRAD, and that TRIM28 expression levels were positively related to tumor purity (p < 0.001) and the presence of CD4+ T cells (p < 0.001) in BRCA." (PMID 37781084, 2023). "These patients were administered APVAC1, derived from premanufactured unmutated tumor antigens, followed by APVAC2, derived from targeted tumor neoepitopes personalized from mutations in individual tumors (APVAC1: CD8+; APVAC2: CD4+)." (PMID 37111620, 2023). "In the ARG-ST1 and ARG-ST2 subtypes with good prognosis, tumour suppressor immune cell infiltration, for instance, B cells and CD4+ T cells, was observed to be considerably increased." (PMID 36844873, 2023). "cDCs are composed of two major branches: tumour‐associated antigens can be presented by cDC1s to cytotoxic CD8+ T lymphocytes, whereas cDC2 cluster cells are more focused on stimulating CD4+ T‐cell responses through major histocompatibility comlex (MHC) II." (PMID 36808888, 2023). "Immunomodulatory activity; Regulate the production of cytokines and chemokines; Induce Tregs; Anti-inflammatory activity; Promote the accumulation of effector CD8+T cells; Suppress tumor-derived CD4+CD25+Tregs." (PMID 37035188, 2023). "TGF-β mediated transformation of resting CD4+ T cells into FoxP3+ Treg cells; lead to tumor metastasis." (PMID 37868967, 2023).
tumor (continued). "Tim-3 plays an important role in the development and progression of gastric cancer, while its level of expression on CD4 + T cells influences clinicopathological parameters such as tumor size, lymph node metastasis, and depth of tumor invasion." (PMID 37567938, 2023). "Recent work has demonstrated that CD4+ T cells provide help to CD8+ T cells by CD40L-dependent licensing of cDC1s during the primary tumor response." (PMID 37400675, 2023). "As this result was similar to tumor growth after both CD4+T and CD8+T depletion with antibodies, it provides solid evidence that rechallenged tumors clearance can be independent of peripheral T cells." (PMID 37407600, 2023). "Interrogation of anti-tumour immunity revealed tumour infiltration by CD4+ T cells, and activation of B, NK, and dendritic cell responses, as well as tumour-reactive serum IgG." (PMID 37153626, 2023). "Inhibition of B7-H3 upregulates cytotoxic CD4+CD25-CD38+CD39+ T cells leading to immune-mediated suppression of tumor progression and development." (PMID 36869048, 2023). "The presentation of antigens by DCs resulted in significantly enhanced anti-tumor responses in both prophylactic and therapeutic tumor models, dependent on CD4+ and CD8+ T cells." (PMID 38258035, 2023). "At the tumor site, mice consistently displayed high percentages of tumor-infiltrating CD8+ cells, elevated levels of IFNγ expression in effector CD4+ and CD8+ T cells, and a substantial loss of Tregs." (PMID 37189748, 2023). "The tumor showed a large amount of CD8+ and CD4+ T cell infiltration around the tumor, and 90% of tumor cells were positive for PD-L1." (PMID 36788154, 2023). "Less number of PD-1+ and CD4+PD-1+ cells in the tumor microenvironment were observed in tumor with high levels of GC." (PMID 37114049, 2023). "Another similar system based on the NFAT reporter was developed to identify tumor specific CD4 T cells by fusing murine MHCII with the signaling domains of TCR resulting in generation of pMHC-TCR (MCR) hybrid molecules." (PMID 38149253, 2023). "For example, interleukin-2 (IL-2) is an important immunomodulatory cytokine, mainly produced by CD4-positive (CD4+) T cells, and thus can be utilized to target some tumor cells that overexpress interleukin-2 receptor (IL-2R)." (PMID 37508840, 2023). "Our data indicated that NLRP3 inflammasome in MDSCs was activated by arachidonic acid through FATP2 during fatty graft injury, and it further induced the IL-17 production of CD4+ T cells, promoting the tumour recurrence post liver transplantation." (PMID 37916155, 2023). "In this study, we found that among tumor-infiltrating CD4 T cells, TNFR2 is quite selectively expressed by Foxp3+ Tregs." (PMID 36865537, 2023). "B lymphocytes can enhance the cytotoxic activity of T cells, the phagocytosis by macrophages, the NK cells’ function of tumor killing, the tumoricidal effect by granzyme B secretion, and the CD4+ and CD8+ T cells’ priming." (PMID 37046842, 2023). "Analysis of lymphocyte populations revealed that the tumor–immune interactome in YUM-mGFP had a larger proportion of CD4+ T cells and Tregs interacting with the tumor compared to YMR-mGFP, with Tregs having the highest percentage of BFP+ expressing cells." (PMID 37871202, 2023). "Accompanying these changes in the composition of CD4+ TILs, the proportion of CD4+ FoxP3+T-bet+ cells increased during tumour outgrowth." (PMID 37153625, 2023). "Further studies showed that the infiltrating CD4+ T cells were decreased to some extent in tumour tissues of WT and KO mice depleted of MPs and NPs." (PMID 36419386, 2023).